INS (insulin)
Diseases named in the same sentence as INS in open-access papers (continued):
Sharing a sentence is not in itself a finding about the gene and the disease.
hyperlipidemia (continued). "In an insulin-resistant state, insulin is unable to adequately downregulate lipolysis; thus, free fatty acids are released from adipose tissue into circulation (contributing to hyperlipidemia) and transported to the liver." (PMID 28335515, 2017). "Since maternal hyperlipemia is higher in the GDM treated with insulin, with respect to both GDMs under dietary treatment or controls, it could be desirable to reduce lipemia in these subjects to avoid excessive placental fat transfer to the fetus." (PMID 28587267, 2017). "Using a gene therapy strategy, we previously found that high-fat diet-fed mice had decreased body weight gains, improved circulating lipidemia and greater insulin sensitivity following GLP-1 treatment.These findings inspired us to explore the local effects of GLP-1 on adipose tissues." (PMID 27504979, 2016). "The postprandial effects of dairy protein have been investigated extensively, and recent studies point to whey protein in particular as having potentially advantageous effects such as reduced postprandial glycemia and lipemia, potentially mediated by an increased postprandial insulin response." (PMID 26927166, 2016). "This study, in addition to previous evidence of butyrate effect in increasing fatty acid oxidation in the liver, muscle and brown adipose tissue, suggests that butyrate may also target white adipocytes to combat hyperlipidemia and enhance insulin sensitivity." (PMID 26713737, 2015). "The main pharmacological effects attributed to nuciferine include smooth muscle relaxation, amelioration of hyperlipidemia, stimulation of insulin secretion, vasodilation, induction of hypotension, anti-arrhythmic properties, and antimicrobial and anti-HIV activities." (PMID 23691094, 2013). "Additionally, DR group had a higher proportion of hyperlipidemia and higher prevalence of insulin therapy than the DM controls (P < 0.01 and P < 0.001, resp)." (PMID 23864767, 2013). "Destruction of β-cells leads to depletion of plasma insulin, which results in hyperlipidemia." (PMID 21206623, 2010). "Despite the usual response of insulin infusion in treatment of severe hyperlipidemia, another report emphasizes that despite aggressive management with insulin infusion, patients may require an extended hospitalization to achieve acceptable triglyceride levels." (PMID 39958046, 2025). "In addition, the results showed reliable differences in some nutrient intake, with higher levels of omega-6 and zinc in participants with hyperlipidemia, and lower levels of beta-carotene, tocopherol, resistant starch, pectin and oxalic acid in the insulin-resistant group." (PMID 39062174, 2024). "In addition to these, there were also enhanced insulin and hyperlipidemia." (PMID 36979879, 2023). "Defective lipid metabolism promotes hyperlipidemia and ectopic lipid accumulation, and lipid overload in non-adipose tissue is associated with impairment of insulin signaling pathways and subsequent reduction in muscle glucose uptake, thereby resulting in muscle IR." (PMID 37667364, 2023). "The effective relationship between insulin-secreting cells and insulin target tissues (pancreas, adipose tissue, liver, and skeletal muscle) maintains metabolic homeostasis in response to physiological fluctuations in glycemia or lipemia, in response to food intake or starvation." (PMID 35625904, 2022). "The results suggest that compared with the normal control group, mice with hyperlipidemia have different biological processes that may involve monounsaturated fatty acid biosynthesis processes, cellular response to insulin stimulation, steroid decomposition processes, and response to fatty acids." (PMID 36147301, 2022). "However, in the current study, we do not observe significant benefits of low-dose GA administration on diet-induced metabolic disorders, including hyperlipidemia, hepatosteatosis, adipogenesis, or insulin resistance, in the Apoe KO mouse models fed with high-fat WTD." (PMID 35652108, 2022).
hyperlipidemia (continued). "Furthermore, the GO and KEGG analysis of S-T, S-T–pathway network, and KEGG pathway enrichment of 10 common genes between regulated DEGs and S-T all indicated that HTJZD exerted therapeutic action on hyperlipidemia by modulating lipid metabolism and insulin resistance." (PMID 33936248, 2021). "Therefore, attenuating hyperlipidemia via regulating lipid metabolism and insulin resistance could be effective solutions to reduce the biosynthesis of lipid and boost lipid consumption." (PMID 33936248, 2021). "In addition, because adiponectin is considered a functional leptin antagonist, subsequently, the reduction of leptin suggests a possible improvement in adiponectin’s activity: insulin sensitivity, adequate adipogenesis, and amelioration of hyperlipidemia showing lipid homeostasis." (PMID 32120804, 2020). "The lack of adiponectin exacerbates lipoatrophy and hyperlipidemia, and this may be due–at least in part–to the diminished insulin signaling and the selective loss of the caveolin-1 complex." (PMID 25339419, 2014). "Thus, we speculate that the improvement of hyperlipidemia in ezetimibe-treated mice might be attributed to the improvement of first phase insulin secretion." (PMID 23118741, 2012). "Results obtained in this study indicate that overweight/obese individuals suffering from hyperlipidemia and NAFLD treated with MHD + NS showed significant improvements in HSIs and γGT biomarker, plasma lipid profile, as well as insulin sensitivity." (PMID 40913543, 2025). "MPC inhibition using a second-generation insulin sensitizer, MSDC-0602 K (MSDC), dampened pulmonary inflammation and promoted lung recovery, while concurrently reducing blood glucose levels and hyperlipidemia following viral pneumonia in obese mice." (PMID 36821695, 2023). "Hyperlipidemia facilitates the development of T2DM via inducing apoptosis of pancreatic β-cells, the downregulated biosynthesis and secretion of insulin, and abnormality in glucose metabolism." (PMID 35282431, 2022). "In dogs with CS, hyperlipidemia can result from downregulation of LDL receptors and decreased liver uptake of LDL and/or development of insulin resistance, which impairs lipoprotein lipase activity." (PMID 35448493, 2022). "By contrast, in over-nutrition induced insulin resistant monkeys, elevated serum TMAO levels corresponded with skeletal muscle hyperlipidaemia indicating that insulin induced lipogenesis was functional." (PMID 34445033, 2021). "The result showed four key pathways (P< 0.05), namely, steroid hormone biosynthesis pathway, insulin signaling pathway, cholesterol metabolism pathway, and linoleic acid metabolism pathway, involved in HTJZD in treating rats with hyperlipidemia." (PMID 33936248, 2021). "Because a high-energy diet impaires both glucose tolerance and insulin tolerance, we used the HFHS diet-fed ApoE−/− mice as a model for T2DM and hyperlipidemia." (PMID 28091547, 2017). "For example, OEA decreases food intake and lowers hyperlipidaemia in obese rats via PPARα activation and both OEA and PEA can stimulate insulin and GLP-1 secretion via activation of GPR119." (PMID 24593280, 2014). "Patients receiving insulin or diuretic treatments also were more likely to have HUA, while those with hyperlipidemia were less likely to have HUA." (PMID 22125626, 2011). "The promotion of hyperlipidemia by TNF-α is primarily mediated by stimulation of hepatic lipid synthesis and adipose lipolysis, along with suppression of triacylglycerol clearance and inhibition of insulin-stimulated de novo lipogenesis (in adipose tissue)." (PMID 39204094, 2024). "The glucagon to insulin ratio was a significant predictor even after adjusting for HbA1c, LDL-C, and use of hyperlipidemia medications, and the same was true after additionally adjusting for incretins (iGLP-1, iGIP), hsCRP (cardiovascular risk factor), fibrinogen, and uric acid." (PMID 37762748, 2023).
hyperlipidemia (continued). "Earlier studies showed that hyperlipidemia is considered a hazard factor for T2DM, and lipid metabolism disturbance may block insulin secretion and lead to impaired insulin sensitivity." (PMID 36160420, 2022). "It was also shown that primary insensitivity to insulin does not appear to be fundamental to the pathogenesis of hyperlipidemia in familial dysbetalipoproteinemia." (PMID 35884932, 2022). "Furthermore, T2DM patients receiving SGLT2i displayed higher hyperlipidemia, coronary artery disease, and were taking more GLP-1 agonists, insulin, metformin, statins, aspirin, and ACEI/ARB medications." (PMID 35710921, 2022). "Similar results were found for patients who were male, without hyperlipidemia, and did not take metformin, sulfonylureas, or insulin." (PMID 35600378, 2022). "The pathway analysis showed that DO might affect diverse signaling pathways related to the pathogenesis of hyperlipidemia, including PPAR signaling pathway, insulin resistance, AMPK signaling pathway, and non-alcoholic fatty liver disease simultaneously." (PMID 35502176, 2022). "MLT efficiently prevented hyperlipidemia and enhanced HDL-C, which could be related to increased insulin secretion, which enhances lipid storage in adipocytes." (PMID 33748504, 2021). "The combination-treatment of heparin and insulin is efficient for reducing triglycerides in a short time, and the combination of cholesterol absorption inhibitor and fibrates is stably decreasing HTG / hyperlipidemia over a long term." (PMID 33080702, 2020). "Western diet fed animals are obese, insulin resistant and hyperlipidemia whereas the MCD diet fed animals had weight loss, but are not insulin resistant or hyperlipidemia." (PMID 30885145, 2019). "The mice on the MCD diet are not obese, actually losing significant body weight (30%), and are not insulin resistant or hyperlipidemia during disease progression." (PMID 30885145, 2019). "The improvement of insulin immunoreactivity as well as pancreatic islet morphology and diameter could elucidate the upregulation of serum insulin level and the decrease in FBG, thus improving hyperlipidemia in diabetic rats." (PMID 29686746, 2018). "The risk reduction was 40% (aRR = 0.60, 95% CI: 0.37–0.98, P = 0.04) after controlling for age, gender, ethnicity, CCI, DCSI, nephropathy, hyperlipidemia, serum creatinine >2.0 mg/dL, HbA1c and concurrent medications including statins, ACEI, sulfonylurea and insulin, and year of presentation." (PMID 29463812, 2018). "In an insulin-resistant state, hypertriglyceridemia is primarily due to an increased hepatic production of very low density lipoprotein (VLDL) particles, postprandial hyperlipidemia, and low lipoprotein lipase (LPL) levels." (PMID 30200612, 2018). "We show that adding 20 g of whey protein to breakfast increases the acute insulin response, without influencing glycemia, lipemia, or appetite sensations compared to an identical meal without additional whey in young healthy males." (PMID 26927166, 2016). "In the absence of both insulin and adiponectin, severe lipoatrophy and hyperlipidemia lead to lethality." (PMID 25339419, 2014). "A-FABP-deficient mice also showed a significant decrease of vascular atherosclerosis in the absence of differences in serum lipids or insulin sensitivity in hyperlipidemia model mice, and this effect was attributed to the action of A-FABP in macrophages." (PMID 21600061, 2011). "Interestingly, the treatment of PTP at a high dosage could dramatically enhance the insulin sensitivity in HFD-fed obese mice, which was salutary to the prevention of hyperlipidemia." (PMID 39063332, 2024). "Particularly, fish oil has more potential on alleviating hyperlipidemia, but might have negative effect on liver function; while olive oil showed superior advantages on protecting islets function and insulin sensitivity." (PMID 38501107, 2024).
hyperlipidemia (continued). "However, DEP ingestion did not aggravate (ApoE−/−), or induce (C57BL/6 mice) atherosclerotic plaques, and no metabolic alteration (glucose tolerance, resistance to insulin, or lipidemia) was recorded." (PMID 33563307, 2021). "A-FABP-deficient mice also show a significant decrease in vascular atherosclerosis in the absence of differences in serum lipid levels or insulin sensitivity in a model of hyperlipidemia, and this effect is due OR has been attributed to the effects of A-FABP on macrophages." (PMID 22433902, 2012). "However, morning exercise is superior to night exercise in enhancing insulin sensitivity and glucose transport, but night exercise is likely to improve mitochondrial networks and morphology through CLOCK–mitophagy and further alleviate apoptosis, thereby reducing fat infiltration and hyperlipidemia." (PMID 36012573, 2022). "Hyperlipidemia did not change concentrations of LH, FSH, 17-β-E2, 17α-OHP, glucose, or insulin." (PMID 34501389, 2021). "For patients with or without OHA/insulin therapy, high-dose RCEG can be administrated to enhance the glycemic control, allowing the patient to approach the targeted goal of HbA1c <7% and improving hyperlipidemia at the same time." (PMID 33568997, 2020). "In our study, with a mouse model exhibiting IR but no other T2DM features, which also had hyperlipidaemia due to a high-fat, high-cholesterol diet, DAPA treatment during the glucose challenge did not change glucose levels, despite increased insulin plasmatic concentration." (PMID 33287201, 2020). "However, hyperlipidemia with increased hepatic levels of CHOL and TGs and fat vacuoles were seen in AuNPs-treated rats, suggesting a hyperlipidemic effect independent of modulating peripheral glucose or insulin signaling." (PMID 36677854, 2023).
insulinoma (690 papers, 1988 to 2026). "Endocrinological assessment demonstrated positive anti-glutamic acid decarboxylase and anti-insulinoma-associated antigen-2 (IA-2) antibodies with reduced endogenous insulin secretion." (PMID 41728451, 2026). "The lack of increase in plasma glucose following glucagon was not consistent with the expected response seen in conditions associated with high insulin states such as insulinoma." (PMID 40083398, 2025). "In nesidioblastosis, SACST should show a diffuse pattern with doubling or tripling of the basal hepatic venous serum insulin concentration in multiple arteries, whereas an insulinoma is typically associated with a focal secretion pattern in a single artery." (PMID 40395710, 2025). "Insulinomas are the most common functional pancreatic neuroendocrine tumors (PanNETs) that produce insulin and cause the hypoglycemic syndrome." (PMID 40281248, 2025). "Insulinoma is a rare pancreatic neuroendocrine neoplasm caused by pancreatic beta cell tumor or beta cell proliferation resulting in excessive insulin secretion." (PMID 39897806, 2025). "Insulinomas are uncommon tumors in the pancreas that result in the overproduction of insulin, which can cause frequent episodes of low blood sugar." (PMID 40486356, 2025). "The following autoantibodies were measured: insulin autoantibodies (IAAs), glutamic acid decarboxylase autoantibodies (GADAs), and insulinoma-associated antigen-2 autoantibodies (IA-2As)." (PMID 40362176, 2025). "Screening is performed in capillary blood, examining different islet autoantibodies (autoantibodies against insulin, glutamic acid decarboxylase-65, insulinoma-associated antigen-2 and/or zinc transporter-8)." (PMID 39753267, 2025). "Insulinoma is a very uncommon type of pancreatic endocrine tumor that causes excessive secretion of insulin within the body." (PMID 40124204, 2025). "The increase in insulin considered diagnostic for an insulinoma or nesidioblastosis is an insulin ratio of >2." (PMID 40395710, 2025). "The primary screening method involves testing for islet autoantibodies, including insulin autoantibodies, glutamic acid decarboxylase autoantibodies, insulinoma associated-2 autoantibodies, and zinc transporter-8 autoantibodies." (PMID 39930327, 2025). "The patient was diagnosed with endogenous hyperinsulinemic hypoglycemia, a condition characterized by abnormally high insulin levels leading to low blood glucose, commonly associated with insulinoma." (PMID 39391450, 2024). "Measurement of serum insulin concentrations during a hypoglycemic episode can help distinguish IAS from insulinoma and other causes, as insulin concentrations are usually above 1000 mU/L." (PMID 39347250, 2024). "This is in line with previous findings, as a higher Ki-67 PI, a larger tumour diameter and a scarce insulin expression have all been associated with aggressive insulinomas." (PMID 37894845, 2023). "Deficiency of Rab26 promotes insulin secretion, which was independently verified by Rab26 knockdown in pancreatic insulinoma cells." (PMID 37289842, 2023). "Although rare, the commonest cause of endogenous hyperinsulinaemic hypoglycaemia is insulinoma, which is characterised by inappropriately high insulin and/or proinsulin, high C-peptide and suppressed or low BOHB in the serum." (PMID 37892096, 2023). "An indirect approach is to monitor autoantibodies against insulin, the insulinoma-associated tyrosine phosphatase- like protein (IA-2), the 65-kDa glutamic acid decarboxylase isoform (GAD65), and zinc transporter 8 (ZnT8)." (PMID 37026004, 2023). "Examine association between serum insulin concentration and survival and clinical disease stage in dogs with insulinoma." (PMID 37194422, 2023). "Information regarding serum insulin concentration in dogs newly diagnosed with insulinoma and its association with clinical stage and survival time is lacking." (PMID 37194422, 2023).